OR4D6 (olfactory receptor family 4 subfamily D member 6)
Description:
Odorant receptor.
Synonyms: OR11-250
Tractability: Antibody: UniProt places it where antibodies can reach, with medium confidence; UniProt predicts a signal peptide or a membrane-spanning region; its Gene Ontology location is reachable by antibodies, with medium confidence.
Gene: Protein-coding gene on chromosome 11 (59,456,961 to 59,457,905, forward strand). Ensembl gene ENSG00000166884.
Subcellular location: Cell membrane
Pathways (Reactome):
Sensory Perception: Expression and translocation of olfactory receptors
Gene Ontology:
Molecular function: olfactory receptor activity; G protein-coupled receptor activity
Biological process: detection of chemical stimulus involved in sensory perception of smell; G protein-coupled receptor signaling pathway
Cellular component: plasma membrane; membrane
Genetic constraint (gnomAD): Loss-of-function variants: 11 observed, 15.15 expected, observed/expected ratio (o/e) 0.73, 90% interval 0.46 to 1.2. The upper end of that interval is the gene's LOEUF score, 1.2, which puts it in group 5 of 6, group 1 being the genes least tolerant of losing a copy. Missense variants: 367 observed, 400.44 expected, observed/expected ratio (o/e) 0.92, 90% interval 0.84 to 1. Synonymous variants: 165 observed, 162.7 expected, observed/expected ratio (o/e) 1.01, 90% interval 0.89 to 1.15.
Homologues: Orthologues: chimpanzee OR4D6 (96% identical), macaque OR4D6 (93% identical), mouse Or4d6 (88% identical), rat Or4d6 (88% identical), dog OR4D6 (87% identical), rabbit OR4D6 (85% identical), guinea pig OR4D6 (83% identical). Paralogues in human: OR4D9 (67% identical), OR4D11 (66% identical), OR4D10 (65% identical), OR4D2 (60% identical), OR4D5 (60% identical), OR4D1 (59% identical), OR4K14 (46% identical), OR4C6 (46% identical), OR4Q3 (46% identical), OR4E2 (45% identical), OR4A47 (45% identical), OR4N2 (45% identical), and 116 more.
Diseases named in the same sentence as OR4D6 in open-access papers:
OR4D6 is named in the same sentence as 1 disease in open-access papers, as found by Europe PMC text mining. Sharing a sentence is not in itself a finding about the gene and the disease. The quoted sentences say what the papers report.
cancer (1 paper, 2021). A tumor composed of atypical neoplastic, often pleomorphic cells that invade other tissues. "As opposed to the majority of the selected targets, that have established oncogenic roles, NDNF and OR4D6, to the best of our knowledge, have no previously known association with cancer progression or drug resistance." (PMID 33767353, 2021).